CRP (C-reactive protein)
Diseases named in the same sentence as CRP in open-access papers (continued):
Sharing a sentence is not in itself a finding about the gene and the disease.
Arthritis (continued). "Our findings demonstrate that age at diagnosis; the presence of arthralgia/arthritis, malignancy, fever, anti-Jo-1 antibodies, and anti-MDA5 antibodies; and ESR and CRP levels were associated with ILD in patients with PM/DM." (PMID 27171228, 2016). "The CRP level can also provide an indication of treatment efficacy, with decreased CRP reflecting effective treatment against arthritis, and sustained high CRP reflecting a poor treatment response." (PMID 27716329, 2016). "The 19-week-old vehicle-treated CYP27B1−/− CIA mice had increased cumulative arthritis scores and levels of serous rheumatoid factors and C-reactive protein." (PMID 27763638, 2016). "All patients with fever had a significantly higher ESR, CRP level, platelet count, and had more arthritis (sacroiliac joint, ankle, calcaneus) or enhesitis than the non-fever group." (PMID 26030261, 2015). "Previous studies of ISIS-CRPRx in rodent models of RA (that is, CRP transgenic mice with collagen-induced arthritis) demonstrated improvement in the clinical signs of arthritis." (PMID 25885521, 2015). "ISIS-CRPRx has been tested in a rodent model of RA (that is, CRP transgenic mice with collagen-induced arthritis) and was shown to improve the clinical signs of arthritis." (PMID 25885521, 2015). "One study demonstrated that high CRP levels are associated with incidence of total joint replacement in patients with arthritis and lower levels of CRP correspond to sustained suppression of the disease." (PMID 25114906, 2014). "There was a significant decrease in the CRP in the δ-tocotrienol and glucosamine-treated group (P > 0.05) when compared to the arthritis alone group." (PMID 25114906, 2014). "γ-tocotrienol significantly reduced the arthritis-induced changes in body weight, CRP, TNF-α, SOD and the total GSH levels." (PMID 24940448, 2014). "Compared with the control, substantially reduced arthritis scores, and CRP levels, with improvements in histology and bone erosion scores, were observed with a dose of 20 mg/kg of olokizumab." (PMID 24670876, 2014). "In several studies there is a significant correlation between IL-17 levels and progression to arthritis or a more aggressive form of disease or C-reactive protein levels." (PMID 25253467, 2014). "In the present study, an increased CRP level was observed in the circulation of rats with arthritis and treatment with γ-tocotrienol significantly inhibited the arthritis-induced CRP changes observed." (PMID 24940448, 2014). "There was a significantly elevated CRP concentration observed in the untreated arthritis group and the arthritis group treated with γ-tocotrienol, when compared with the control rats (P<0.05)." (PMID 24940448, 2014). "The δ-tocotrienol and glucosamine groups still had significantly lower levels of CRP by the end of the experimental cycle compared to arthritis alone group." (PMID 25114906, 2014). "Physical examination revealed arthritis of the left knee, and laboratory findings showed a mild increase in C-reactive protein (CRP) level and erythrocyte sedimentation rate (ESR)." (PMID 24191219, 2013). "PCA of NMR spectra of serum from 84 patients with early arthritis (in group 1) in whom the CRP levels were known showed a broad spread on the scores plot." (PMID 23740368, 2013). "A significant increase (P < 0.05) in C-reactive protein level was seen in arthritis only rats until 45 days compared to control rats." (PMID 23476804, 2013). "In early arthritis, we were able to stratify the patients according to the level of current inflammation, with C-reactive protein correlating with metabolic differences in 2 separate groups (P < 0.001)." (PMID 23740368, 2013). "Solomonsterol A rescued mice from systemic inflammation were assessed by measuring arthritis score, CRP and cytokines in the blood." (PMID 24368568, 2013).
Arthritis (continued). "Preclinical work in a rhesus monkey collagen-induced arthritis model demonstrated suppression of C-reactive protein (CRP) and altered antibody response toward type II collagen with a CCR5-antagonist, SCH-X." (PMID 22251436, 2012). "Disease severity, functional disability, counts of swollen and/or tender joints, duration of RA, frequency of arthritis surgery, and C-reactive protein (CRP) levels were assessed by rheumatologists." (PMID 22156289, 2012). "The level of CRP decreased by 19.78% in plasma measured on day 28 in the arthritis group treated with MTX in comparison to AA." (PMID 23118593, 2012). "Administration of carnosine+methotrexate decreased the level of CRP in plasma by 23.98% in comparison to the untreated arthritis group (AA-CARN+MTX vs. AA, +++p<0.001)." (PMID 23118593, 2012). "The serum markers of inflammation and arthritis, such as C-reactive protein and rheumatoid factor, were also reduced in the BA-treated arthritic rats." (PMID 19770265, 2011). "In the placebo + MTX group, changes in ICAM-1 and CRP levels were significantly correlated with the number of joints with active arthritis at week 14 (r = 0.64, p < 0.0001; r = 0.38, p = 0.004; respectively) (data not shown)." (PMID 20822542, 2010). "Although this is contrary to what is generally reported in the literature, Green and colleagues in their study of 63 early arthritis patients also found a protective effect of elevated CRP for persistent arthritis." (PMID 19796386, 2009). "Several proteins correlated with arthritis severity, psoriasis burden, and CRP." (PMID 41851388, 2026). "In a study of arthritic rats, evaluation of serum markers of arthritis, such as C-reactive protein (CRP) and rheumatoid factor (RF), showed that the group treated with B. breve had significantly reduced levels of these markers compared to the untreated control rats." (PMID 40207278, 2025). "In the present study, fever, arthralgia/arthritis, and high CRP favored vasculitis." (PMID 40385871, 2025). "The circulating markers of inflammation, CRP and IL6, may also be associated with inflammatory conditions such as arthritis or infections." (PMID 40137085, 2025). "We utilized C-reactive protein (CRP) to assess whether inflammatory status in arthritis patients modify this relationship." (PMID 40904459, 2025). "During the early and pre-clinical stages of RA, as well as in models of experimentally induced arthritis, CRP may exert beneficial effects, possibly through its role in immune complex formation and complement activation." (PMID 40943152, 2025). "Future research should explore whether combining NPAR with CRP/hsCRP or other clinical parameters could further enhance predictive models for arthritis outcomes." (PMID 40718497, 2025). "Understanding the relationship between CRP levels and mortality in arthritis patients could inform health education and promotion strategies aimed at reducing inflammation and improving long-term outcomes." (PMID 39980916, 2025). "Thus, both cytokines, IL-17 and IL-6, which are critical than TNF-α in arthritis, are inhibited by CRP." (PMID 38650931, 2024). "We tested the hypothesis that CRP changes its structure in the synovium, binds to immobilized ICs, and subsequently protects against the development of arthritis." (PMID 38650931, 2024). "Clinical manifestations such as fever, arthritis, rash, and myalgia, along with increased levels of inflammatory indicators such as C-reactive protein (CRP), erythrocyte sedimentation rate (ESR), and ferritin were observed during different follow-up assessments." (PMID 38504360, 2024). "However, high-sensitivity CRP is usually driven by other inflammatory conditions such as infection, arthritis, etc., and cannot specifically reflect the local inflammation of carotid atherosclerosis." (PMID 38434202, 2024).
Arthritis (continued). "The current study aimed to clarify the role of lipocalin in Mosul patients with new-onset arthritis by assessing its association with indicators of inflammation (IFN-γ, CRP, and ESR), bone density (vitamin D3 and calcium), and metabolic dysfunction (triglyceride-glucose (TyG) index)." (PMID 38765271, 2024). "We did not report any disease activity markers (WBC, ESR, CRP, arthritis, tenditis, BASDAI, VAS) to be significantly associated with our endpoint." (PMID 38743252, 2024). "After further adjusting for HDL-C, LDL-C, creatinine, and CRP levels, the reanalyzed data showed that the association between dynapenic abdominal obesity and new-onset arthritis did not change significantly." (PMID 39367987, 2024). "As an inflammatory marker substance, CRP is elevated in some patients with arthritis." (PMID 38347551, 2024). "Increased CRP levels also signal a worse prognosis of arthritis." (PMID 38675650, 2024). "Association between biomarker levels at baseline and improvements in JIA-American College of Rheumatology (ACR) criteria responses or baseline disease activity (measured by Juvenile Arthritis Disease Activity Score in 27 joints using C-reactive protein [JADAS27-CRP]) were assessed." (PMID 38918871, 2024). "IC-complexed CRP, through an as yet undefined mechanism, directly or indirectly, inhibits the production of IL-17 and eventually protects against the initiation of the development of arthritis." (PMID 38650931, 2024). "The anti-inflammatory cytokine IL-10 was significantly decreased (53% decrease, P = < 0.001), while the inflammatory markers IL-17 (2.8-fold increase, P = < 0.001) and CRP (9.38 folds increase, P = < 0.001) increased in the untreated arthritis group versus the control group." (PMID 37389660, 2023). "The elevation of the serum hs-CRP level has been shown to coincide with SI joint inflammation." (PMID 36615149, 2023). "In patients with mild to moderate arthritis, CRP was higher than normal and a dosing regimen of 474 ml per day of cherry juice from fresh‐frozen cherries for six weeks resulted in a 23% reduction in CRP." (PMID 35119142, 2022). "Due to nausea and elevation of liver enzymes, the dosage could not be increased to more than 8 mg/week, and 4 months later, she continued to have arthritis in multiple joints of her hands and the knees, and CRP remained elevated at 3.82 mg/dL." (PMID 35363175, 2022). "A year later, her arthritis worsened, and CRP increased to 10.29 mg/dL." (PMID 35363175, 2022). "In summary, arthritis was more common in SSc-patients with continuously elevated CRP levels." (PMID 36743676, 2022). "Moreover, elevated serum CRP is rarely seen in IIM, and is mostly observed in IIM-associated arthritis, ILD or cancer." (PMID 35154129, 2022). "After starting tocilizumab, her arthritis improved, and CRP normalized." (PMID 35363175, 2022). "This is a relevant finding, because we observed an association of ICOS expression on Treg with PsA disease activity as measured by PASDAS (range 0–10), which takes arthritis, enthesitis, dactylitis, C-reactive protein, physician disease activity score and two PROs into account." (PMID 36450783, 2022). "Arthritis is more frequent in CRP + compared to CRP- SSc patients." (PMID 36743676, 2022). "The top 10 important variables were disease duration, percentage of lymphocytes (L%), percentage of neutrophils (N%), neutrophil-to-lymphocyte ratio (NLR), sex, C-reactive protein (CRP), shawl sign, arthritis/arthralgia, V-neck sign, and anti-PM-Scl75 antibodies." (PMID 35237262, 2022). "Moreover, no significant between-group difference was observed in terms of serum C-Reactive Protein (CRP) levels before arthritis induction and at the end of the experiment." (PMID 33799992, 2021).
Arthritis (continued). "CAOSD patients were significantly younger than patients with uncomplicated AOSD and had less arthralgia and arthritis; more frequent hepato-splenomegaly, pulmonary and/or cardiological involvement; and a higher heart rate; their CRP and ferritin levels were higher." (PMID 34635157, 2021). "As compared traditional biomarkers, PTX3 has been found to be a sensitive non-invasive biomarker of clinical arthritis activity in RA, indicating that ER, CRP and PTX3 may play a significant role in improving arthritis." (PMID 34447637, 2021). "In this multicentre rheumatological observational cohort study, we identified 68 patients with WD, all but one with rheumatological involvement, of whom 60 had arthritis, 63 had elevated CRP levels, 20 had ineffective biological therapy, and all had a response to antibiotics." (PMID 34112875, 2021). "The only study that showed an association between serum CRP at study entry and development of arthritis included patients with CSA and did not select on the presence of autoantibodies." (PMID 34211986, 2021). "Physical activities such as running, walking, and jogging are proven to decrease this risk of cardiovascular complications among this sub-group of arthritis by reducing the pro-inflammatory leukotrienes such as Interleukin (IL)-6, C-reactive protein (CRP), tumor necrosis factor (TNF) alpha." (PMID 34722047, 2021). "Subsequently, we studied whether the transcriptomic biomarkers obtained were associated with IA development independently of known risk factors (CRP, ACPA, and MRI-detected subclinical joint inflammation)." (PMID 33168080, 2020). "Moreover, IL-7R and IGF-1 remained significantly associated even after correction for known predictors (ACPA, CRP, imaging-detected subclinical joint inflammation; p = 0.039, p = 0.005, respectively)." (PMID 33168080, 2020). "CRP levels reportedly increase during infection, arthritis, and serositis in SLE patients." (PMID 33199770, 2020). "In addition, the JBD patients who received anti-TNF-alpha therapy had higher serum CRP levels at the time of disease onset and higher rates of gastrointestinal symptoms and arthritis/arthralgia." (PMID 31296171, 2019). "Higher concentrations of CRP in the plasma indicate expanded joint changes in arthritis." (PMID 31727971, 2019). "We assessed whether changes in the levels of the objective biomarkers of arthritis (serum CRP, MMP-3) after ABA treatment for 24 weeks were different between the Th17.1-lower and Th17.1-higher groups." (PMID 31747403, 2019). "The indirect pathway from CASP-19 slope (via change in CRP) to arthritis risk was also not significant (p = .188)." (PMID 28604559, 2017). "Change in well-being was associated with arthritis risk; however, change in CRP did not mediate this association." (PMID 28604559, 2017). "The indirect effect of well-being intercept (via CRP at wave 2) on arthritis risk was no longer significant." (PMID 28604559, 2017). "Although K. kingae arthritis is characterized by normal to moderate increase in inflammatory markers, we point out that the patient had a markedly elevated CRP level upon admission, consistent with invasive infection caused by K. kingae of at least several days duration." (PMID 29164082, 2017). "Although change in well-being for the follow up period was associated with arthritis risk, this association was not mediated by change in CRP." (PMID 28604559, 2017). "The improvement in CRP levels supports tissue recovery and functional restoration allowing us to monitor the therapeutic efficacy of Betesil and further supporting its use as a local pharmacological therapy for arthritis pain and functional disability." (PMID 27928713, 2017). "In conclusion, the present study shows that Betesil is well tolerated and displays superior efficacy in reducing pain and functional disability and ameliorating CRP levels, redness, and edema, when compared with diclofenac sodium cream, in patients affected by arthritis and OA." (PMID 27928713, 2017).
Arthritis (continued). "We present 4 pediatric patients who were initially diagnosed with acute pyogenic osteomyelitis or arthritis, based on the elevated white blood cell counts and/or C-reactive protein in addition to the localized high signal intensity on T2-weighted magnetic resonance images." (PMID 27830102, 2016). "Our results showed that nine factors (age at diagnosis, heliotrope rash, arthritis/arthralgia, malignancy, fever, presence of anti-Jo-1 antibody, elevated ESR, presence of anti-MDA5 antibody, and elevated CRP level) were associated with the development of ILD in patients with PM or DM." (PMID 27171228, 2016). "Compared with WT CIA mice, body size was decreased; however, cumulative arthritis scores from 1 to 9 weeks after primary immunization, paw thickness, levels of rheumatoid factors (RFs) and C-reactive protein (C-RP) from serum increased significantly in vehicle-treated CYP27B1−/− CIA mice." (PMID 27763638, 2016). "However, the CRP level was significantly decreased in the γ-tocotrienol group when compared with the CRP levels of the untreated arthritis group (P<0.05)." (PMID 24940448, 2014). "The higher level of CRP observed in the arthritis group confirmed the pathology of the joint and the CRP production may have increased as a result of the activated macrophages and fibroblasts within the synovium of the inflamed joints." (PMID 24940448, 2014). "Higher concentration of C-reactive protein will point toward increased joint changes in arthritis." (PMID 23476804, 2013). "In addition, it has been observed in the clinic that some patients have normal or low levels of ESR or CRP despite extensive arthritis." (PMID 21303509, 2011). "“SpA features” included inflammatory back pain, arthritis, enthesitis (heel), uveitis, dactylitis, psoriasis, Crohn's disease/ulcerative colitis, good response to NSAIDs, family history of SpA, HLA-B27, and elevate C-reactive protein (CRP)." (PMID 23509636, 2011). "Additionally, we utilized C-reactive protein (CRP) to assess whether inflammatory status in arthritis patients modify this relationship." (PMID 40904459, 2025). "Consequently, ligand-complexed CRP, through an as-yet undefined mechanism, directly or indirectly, inhibits the production of IL-17 and eventually protects against the initiation of the development of arthritis." (PMID 38650931, 2024). "The severity of arthritis was evaluated by measuring the ankle diameter and arthritic score, hematological and biochemical parameters (erythrocytes, leukocytes, lymphocytes, monocytes, granulocytes counts, erythrocyte sedimentation rate, C-reactive protein and rheumatoid factor)." (PMID 37860100, 2023). "Furthermore, we did not include data on markers of inflammation that could potentially impact arthritis, such as C-reactive protein and erythrocyte sedimentation rate." (PMID 37608322, 2023). "Recurrent fever and re-elevation of the serum CRP concentration could reflect active arthritis." (PMID 37336934, 2023). "We hypothesized, that arthritis might contribute to CRP elevation." (PMID 36743676, 2022). "In addition, that study found that CKD was significantly associated with the duration of arthritis and high CRP levels, whereas cross-sectional studies have shown that arthritis risk factors are not significant predictors of CKD in patients with RA." (PMID 35207306, 2022). "In addition, oxidative damage to lipids is related to physiologic conditions such as increasing levels of body fat and cholesterol, smoking, and inflammation (reflected in C-reactive protein), which may increase with arthritis and other conditions of aging." (PMID 36225290, 2022). "Interestingly, animal studies indicate that CRP’s association with autoimmune diseases might be reversed, i.e. the onset of multiple sclerosis, arthritis, and lupus, is delayed in CRP transgenic mice." (PMID 33633738, 2020). "However, only a fraction of about one-third of patients with arthritis shows elevated CRP." (PMID 32051028, 2020).